IL6 (interleukin 6)
Diseases named in the same sentence as IL6 in open-access papers (continued):
Sharing a sentence is not in itself a finding about the gene and the disease.
coagulopathy (74 papers, 2005 to 2026). "The increase in IL-6 levels is a classical hallmark of cytokine-storm-related coagulopathy, as this proinflammatory cytokine is known to promote coagulation cascade activation and vascular leakage." (PMID 36298678, 2022). "HsCRP and IL‐6 levels had significant correlations with coagulation parameters, which confirmed that coagulopathy is associated with excessive systemic inflammation." (PMID 33392432, 2020). "If IL-6 is above 10–15 pg/mL, or IL-2R above 600 μ/mL, the probability of coagulopathy risk is higher." (PMID 33747973, 2020). "We specifically hypothesized that in trauma patients, IL-6 blood concentration measured upon ER admission is associated with coagulopathy and predicts the need for an MT." (PMID 34073768, 2021). "However, it has not yet been established whether the post-traumatic changes in circulating IL-6 are associated with coagulopathy." (PMID 34073768, 2021). "Tigecycline is believed to inhibit vitamin K synthesis, affect coagulation factor synthesis, or inhibit the IL-6 mechanism to induce coagulation disorders." (PMID 39611150, 2024). "In the SARS-CoV2 infection, there has been an “infection-induced coagulopathy” phenomenon, resulting from hyperactivation of endothelial cells (due to the increased amount of IL-6) and increased release of tissue factor." (PMID 37834356, 2023). "The current studies have mostly focused on IL-6, and the role of IL-10 in endothelial homeostasis and coagulation disorders needed further investigation." (PMID 37814134, 2023). "Our result demonstrated that inflammation correlates with coagulopathy, but conceivably notvia a direct IL-6 pathway." (PMID 37841828, 2022). "In the present study, we also found that systemic inflammatory indicators C-reactive protein and IL-6 were persistent higher in coagulopathy patients than those in non-coagulopathy patients from the admission day to the coagulopathy onset." (PMID 33564286, 2021). "IL-6 ≥ 350 pg/mL appears to be a reasonable early predictor for coagulopathy and MT within the first 6 and 24 h intervals." (PMID 34073768, 2021). "Coagulopathy was also evident, given that patients in the high-IL-6 group received significantly higher amounts of fibrinogen concentrate and prothrombin complex concentrate within the first 6 and 24 h compared with the low-IL-6 group (p < 0.05 for all)." (PMID 34073768, 2021). "In overt DIC patients and non-overt DIC patients, levels of inflammation-related indicators, such as PCT, high sensitivity CRP and IL-6 were significantly higher than those in non-coagulopathy patients." (PMID 33564286, 2021). "The SHAP analysis of the model suggested that the inflammatory indicators, hs-CRP, IL-6, and IL-2R, are significantly suggestive of coagulation disorders." (PMID 33747973, 2020). "Proinflammatory cytokines, such as IL-6, IL1-β and TNF, are believed to cause the majority of symptoms, such as fever, malaise, and coagulopathies associated with infections." (PMID 21461372, 2011). "Thus, we investigated the correlation between levels of IL-6 and markers of coagulopathy and inflammation." (PMID 37841828, 2022). "Furthermore, MV was associated with derangements in laboratory values, mainly white blood cell (WBC) count and platelets, as well as increased inflammatory/coagulopathy markers (procalcitonin, IL-6, D-dimer and fibrinogen)." (PMID 35455738, 2022). "The second blood collection sample showed that IL-6, ferritin, D-dimer, and PT had a statistically significant negative correlation with theSpO2/FiO2 ratio, suggesting that deteriorating lung function is also correlated with inflammation and coagulopathy." (PMID 37841828, 2022). "An analysis was carried out on the second blood collection after patients had a worsening during treatment to determine whether the incidence of coagulopathy correlates with IL-6 levels, in which the effect of IL-6 and cytokine storm was the utmost." (PMID 37841828, 2022).
coagulopathy (continued). "However, less is known regarding the post-traumatic capacity of IL-6 fluctuations to predict coagulopathy, hemostatic therapy, and transfusion requirements." (PMID 34073768, 2021). "IL-6 levels also positively correlated with coagulopathy markers (APTT, D-dimer), and mortality." (PMID 34571942, 2021). "Plasma IL-6 was higher in patients with coagulopathy than controls, but it's not a risk factor for organ dysfunction by logistic regression." (PMID 33564286, 2021). "The limitation of this study could be unmeasured confounders such as the use of steroid anti-inflammatory medicine (dose and duration) and tocilizumab (interleukin-6 inhibitors) which might have been taken by a few patients before measuring inflammatory and coagulation-disorder markers." (PMID 38610151, 2024). "Furthermore, in contrast to treatments that solely interfere with IL-6, vitamin K not only modulates inflammation but also targets other causes of SARS-CoV-2 induced pathology, including vascular and pulmonary damage as well as coagulopathy." (PMID 35111793, 2021). "TF level was also positively correlated with TNF-α, IL-1β, IL-6, and MPO levels and was negatively correlated with IL-10, indicating that the TF level was closely associated with the inflammatory factors, which may cause coagulation disorders." (PMID 32587471, 2020). "By analyzing laboratory blood tests, we found that coagulopathy, myocardial injury, kidney injury, and increased CRP and IL-6 levels were exhibited more frequently in the severe group than in the non-severe group." (PMID 33693017, 2021). "Endotype 1 patients had low levels of inflammatory markers (ferritin, IL-6, CRP, LDH), low infectious markers (WBC, procalcitonin), and low degree of coagulopathy (PTT, PT), while endotype 4 had higher levels of those markers." (PMID 34859018, 2021). "Labwork showed hemoglobin of 5.9 g/dL, platelet of 55×109/L, coagulopathy, serum C-reactive protein (CRP) of 114.26 mg/L, and interleukin-6 (IL-6) of 146.69 pg/ml." (PMID 33604290, 2020). "Most biomarkers are related to the immune system (SAA,TNF-∝, and IP-10) or coagulopathies (D-dimer, antithrombin, and VWF) and a few have already been established as cancer biomarkers (ACE2, IL-6, IL-4 and IL-2)." (PMID 32935101, 2020). "Additionally, elevated levels of blood IL-6 and CRP occurred more frequently in patients with coagulopathy, and monocyte counts were significantly decreased when coagulopathy occurs." (PMID 33564286, 2021). "The concentration of IL-6 was markedly increased in coagulopathy group, including overt DIC and non-overt DIC patients, compared with non-coagulopathy group on admission." (PMID 33564286, 2021). "Only 4 of 9 overt DIC patients, 8 of 13 non-overt DIC patients, and 62 of 123 non-coagulopathy patients received IL-6 tests." (PMID 33564286, 2021). "Among all studies, interventions with anticoagulant activity or anti-inflammatory activity did not appear to be harmful in patients with evidence of less coagulopathy (as assessed by coagulation tests) or less inflammation (as assessed by IL-6 levels)." (PMID 16280057, 2005). "In addition, high IL-6, regardless of CRP value, associates with hemodynamic dysfunction characterized by reduced systolic and diastolic arterial pressure, coagulopathy, and hepatic and renal dysfunction." (PMID 35634339, 2022). "Additionally, interventions with anticoagulant activity or anti-inflammatory activity did not appear to be harmful in patients with evidence of less coagulopathy (as assessed by coagulation tests) or less inflammation (as assessed by IL-6 levels)." (PMID 16280057, 2005). "Endotype 1 patients had the lowest inflammatory markers (ferritin, IL-6, CRP, ESR, LDH), lowest infectious markers (WBC, procalcitonin), and lowest degree of coagulopathy (PT and PTT, but not significantly < endotype 2)." (PMID 34859018, 2021).
diabetic retinopathy (74 papers, 2007 to 2026). "Interleukin-6 (IL-6) is a cytokine associated with many intraocular inflammatory diseases, such as diabetic retinopathy (DR)." (PMID 36422204, 2022). "Interleukin-6 (IL-6) is implicated in various retinal and vascular complications associated with diabetic retinopathy (DR)." (PMID 36271280, 2022). "In fact, high-throughput sequencing indicated that the coexpressed gene, A2M (A2MD|CPAMD5|FWP007|S863-7) which encodes the α-2-macroglobulin that acts as a carrier of proinflammatory cytokines such as interleukin-1β, interleukin-6, and tumor necrosis factor-α, causes diabetic retinopathy." (PMID 32148491, 2020). "It is well documented that IL-1beta up-regulates adhesion molecules which are in turn vital for the binding of leukocytes to the endothelial surface, whilst IL-6 and IL-8 are among the most essential cytokines implicated in the development of diabetic retinopathy." (PMID 20964838, 2010). "The increased IL-6 expression in Glc25 compared to that in controls was consistent with previous scientific findings on the inflammatory processes in diabetic retinopathy." (PMID 40332752, 2025). "Among inflammatory cytokines, interleukin (IL)-6 and IL-8 are significantly elevated in the eyes of patients with diabetic retinopathy." (PMID 41163032, 2025). "Increased levels of proinflammatory cytokines such as tumor necrosis factor-alpha (TNF-α), interleukin-1 beta (IL-1β), and interleukin-6 (IL-6) have been detected in the vitreous and retina of people with diabetic retinopathy." (PMID 38918766, 2024). "An increase in IL-6 levels in aqueous humor were detected one day after intravitreous BVZ administration for diabetic retinopathy, and 10 days after treatment for proliferative diabetic retinopathy." (PMID 38536827, 2024). "Similar associations between disease severity and cytokine levels have been reported in other retinal disorders, such as diabetic retinopathy, where elevated levels of IL-6, IL-8, and VEGF were correlated with disease progression." (PMID 39202285, 2024). "One of the most well known is interleukin-6 (IL-6), which is a pro-inflammatory cytokine that has been found to be elevated in the AHs of individuals with diabetic retinopathy." (PMID 38731110, 2024). "A comparative analysis between humans and rodents indicates that proinflammatory factors such as TNF-α, IL-1β and IL-6 are correlated with diabetic retinopathy." (PMID 37670018, 2023). "As with the pathogenesis of diabetic retinopathy, the role of IL-6 in AMD is closely tied to the dysfunction of the endothelium, increased oxidative damage, and increased expression of VEGF, leading to angiogenesis and vascular proliferation." (PMID 36902105, 2023). "The exact role that IL-6 plays in the treatment of diabetic retinopathy and diabetic macular edema still needs to be explored further in patients as well." (PMID 36902105, 2023). "Similar properties are described in the literature for IL6, which is elevated in various mentioned retinal disorders, such as retinal detachment, diabetic retinopathy, and age-related macular degeneration." (PMID 35883547, 2022). "VEGFA, AKT1, and IL-6 were recognized as core targets in the network pharmacology prediction study of Astragalus membranaceus in treating the diabetic retinopathy, and the PI3K-Akt signaling pathway role has also been highlighted." (PMID 35607520, 2022). "Curcumin, the main component of turmeric, was capable to slow down inflammation in AMD, diabetic retinopathy or RP through the downregulation of IL6, TNFα, etc.." (PMID 35387197, 2022). "Elevated levels of pro-inflammatory cytokines such as IL-1β, TNF-α and IL-6 were found in the retinae of patients with diabetic retinopathy, as well as in mouse or rat models of diabetic retinopathy." (PMID 35309305, 2022). "The pleiotropic cytokine interleukin-6 (IL-6) is increasingly emerging as an important contributor to the pathology of diabetic retinopathy (DR)." (PMID 36271280, 2022).
diabetic retinopathy (continued). "Our primary interest in IL-6 trans-signaling is in the context of the development and progression of diabetic retinopathy." (PMID 36271280, 2022). "Knockdown of AQP-4 in a model of diabetic retinopathy resulted in increased expression of inflammatory molecules, including IL-6 and VEGF." (PMID 36347836, 2022). "Previous studies provide evidence that IL-6 plays a role in the onset and progression of diabetic retinopathy." (PMID 33919327, 2021). "Through the construction of the protein-protein interaction (PPI) network, we obtained the core targets of Compound-Xueshuantong Capsule in diabetic retinopathy treatment, such as IL6, EFGR, CASP3, and VEGFA." (PMID 32963574, 2020). "In diabetic retinopathy, there is an increase of pro-inflammatory cytokines and chemokines like monocyte chemoattractant protein 1, TNFα, interleukin 1β (IL-1β) and IL-6." (PMID 31739614, 2019). "Demonstration of reduction of IL-6 levels in aqueous has been shown to be an important marker for reduction of vascular endothelial growth factor (VEGF) in patients with diabetic retinopathy on bevacizumab (anti VGEF treatment)." (PMID 29351788, 2018). "In diabetic retinopathy, the expression of proinflammatory IL6 and TNF-α were significantly inhibited after decreasing the expression of HIF-1." (PMID 30662576, 2018). "IL-6, IL-7, IL-8, IFN-γ and IP-10 were reported to be associated with inflammation in diabetic retinopathy, branch and central retinal vein occlusion and choroidal neovascularization." (PMID 28486560, 2017). "The aqueous humor levels of VEGF and IL-6 have been compared with vitreous levels and were found to correlate strongly in diabetic retinopathy patients." (PMID 22511846, 2012). "Various investigators have detected elevated levels of IL-6 in ocular fluid from patients with diabetic retinopathy." (PMID 22312190, 2012). "However, it has been previously shown in a mouse model of early diabetic retinopathy that inhibiting IL-6 trans-signalling with recombinant sgp130Fc reduces oxidative stress caused by an increase in ROS production." (PMID 41597232, 2026). "Similarly, a pro-inflammatory phenotype in T1DM patients with diabetic retinopathy was reported, marked by increased production of IL-6, IL-10, and IL-17A by myeloid cells, alongside reduced IFN-γ production by T cells." (PMID 41280935, 2025). "Additionally, in models of diabetic retinopathy, UA reduced inflammation (IL-6, IL-1β, TNF-α) and oxidative stress by increasing levels of SOD and GSH while decreasing MDA, effects associated with activation of the Nrf2/HO-1 pathway." (PMID 41374004, 2025). "In diabetic retinopathy, the significant elucidation of IL-6′s role has occurred." (PMID 36902105, 2023). "As with diabetic retinopathy, there is also significant evidence from in vitro and animal studies that IL-6 could play a significant role in the disease." (PMID 36902105, 2023). "Indeed, growth factors, such as interleukin-6 (IL-6), have been correlated with diabetic retinopathy progression in PDR." (PMID 34010297, 2021). "The effect of the Compound-Xueshuantong Capsule on diabetic retinopathy may be related to IL6, EFGR, CASP3, and VEGFA." (PMID 32963574, 2020). "Therefore, in our study, the correlation of IL-6 with other biomarkers in the aqueous humor was evaluated in the patients with diabetic retinopathy." (PMID 28969616, 2017). "IL-6 is increased in the vitreous in experimental and clinical diabetic retinopathy." (PMID 27019421, 2016). "This hypothesis has been supported by a publication reporting corresponding aqueous and vitreous levels of VEGF and IL-6 in diabetic retinopathy patients." (PMID 22128233, 2011). "However, there was no report published in the available literature on the role of IL-6 at the early stages of the diabetic retinopathy development in DM type 1 children." (PMID 17641733, 2007).
diabetic retinopathy (continued). "Multiple cytokines and chemokines, such as IL-1β, IL-6, IL-8, TNF-α, and MCP-1, were found to be increased in serum and vitreous of the patients with diabetic retinopathy and DME." (PMID 40564027, 2025). "The role of several cytokines such as IL-6, IL-8, MCP-1/CCL2, and VEGF is well-known in diabetic retinopathy (DR)." (PMID 38338843, 2024). "In patients with diabetic retinopathy, elevated levels of ICAM-1 and VCAM-1 have been detected, likely due to increased IL-6 activation." (PMID 36902105, 2023). "In diabetic retinopathy, METTL3 upregulation was detected in pericytes treated with inflammatory stimuli, such as tumor necrosis factor-α (TNF-α), and interleukin-6 (IL-6)." (PMID 36291060, 2022). "Several studies have investigated the connection between IL-6 and CFT in patients with diabetic retinopathy (DR)." (PMID 36422204, 2022). "The vitreous and aqueous levels of IL-6 and VEGF were significantly correlated with the severity of diabetic retinopathy and with the pathogenesis of diabetic macular edema." (PMID 34575451, 2021). "Advanced glycation end-products or glycation proteins can induce the release of pathophysiological substances such as IL-6, IL-8, MCP-1, ICAM-1, and IP-10 in conditions such as diabetic retinopathy." (PMID 34871313, 2021). "This study is for identifying systemic factors correlating with intraocular levels of interleukin-6 (IL-6) and vascular endothelial growth factor (VEGF) in diabetic retinopathy." (PMID 31396410, 2019). "Similar to RVO and diabetic retinopathy, there are no published trials of IL-6 inhibition in the treatment of neovascular AMD." (PMID 36902105, 2023). "Although there are no formally published case series or trials on the use of IL-6 inhibitors in the treatment of diabetic retinopathy, this remains a promising area for potential exploration." (PMID 36902105, 2023). "The influence of VEGF-A, IL6, and IL8 (angiogenic factors) and MIP1α (leucocyte recruiter molecule) in vitreoretinal disorders has been previously reported for proliferative and/or diabetic retinopathies." (PMID 36567907, 2022). "Likewise, IL-17A, IL-6, and TNF-α are the primary cytokines involved in retinal inflammation, retinal vascular impairment, and the progression of diabetic retinopathy." (PMID 33919327, 2021). "In their study, the decreased TNF-α and IL-6 levels were observed in the subjects with nonproliferative diabetic retinopathy, whilst the presence of proliferative diabetic retinopathy was associated with the increased TNF-α and IL-6 levels." (PMID 23316106, 2012). "Diabetic retinopathy is a multifactorial disease that is associated with not only VEGF, but also other inflammatory cytokines, such as monocyte chemoattractant protein-1, intercellular adhesion molecule 1, interleukin-6, and platelet-derived growth factor." (PMID 37374329, 2023). "Additionally, inflammatory cytokines (TNF-α, IL-1β, and IL-6) produced by CD68-expressing macrophages recruit inflammatory immune cells in the retinas of diabetic animals, crucially contributing to the development and progression of diabetic retinopathy." (PMID 36362313, 2022). "Furthermore, in mice with STZ-induced diabetic retinopathy, intravitreal injection of the MC5R peptidomimetic agonist PG-901 attenuated, while MC5R antagonist PG20N augmented, retinal release of various inflammatory cytokines, such as IL-1α, IL-1β, IL-6, MIP-1α, MIP-2α, and MIP-3α." (PMID 35721571, 2022). "After grouping according to diabetic retinopathy stage, non-proliferative diabetic retinopathy (NPDR) patients with SRF had higher aqueous levels of IL-6 and IL-8, compared to NPDR patients without SRF." (PMID 34697354, 2021). "PRP does not always induce macular edema and reduces the activity of diabetic retinopathy, and ΔFT in PRP treated eyes was statistically correlated with VEGF (r=0.552, p=0.0004) and IL-6 (r=0.647, p<0.0001)." (PMID 23675018, 2007).